HAS2 (hyaluronan synthase 2)
Diseases named in the same sentence as HAS2 in open-access papers (continued):
Sharing a sentence is not in itself a finding about the gene and the disease.
endothelial dysfunction (2 papers, 2020 to 2023). In vascular diseases, endothelial dysfunction is a systemic pathological state of the endothelium (the inner lining of blood vessels) and can be broadly defined as an imbalance between vasodilating and vasoconstricting substances produced by (or acting on) the endothelium. "Our findings suggest hyaluronan increases oxidative stress in the vascular wall and that together with increased EC distance, it is associated with a sex-specific decrease in NO levels and endothelial dysfunction in the aorta of male HAS-2 transgenic mice." (PMID 37176139, 2023). "Our recent study showed that endothelial specific deletion of has2 in mice leads to loss of HA incorporation in glycocalyx, causing endothelial dysfunction and vascular destabilization in multiple tissues, such as kidney, retina and heart." (PMID 32235347, 2020). "The novel findings of the present study are that hyaluronan increases oxidative stress in the vascular wall and that together with increased EC distance, it is associated with a sex-specific decrease in NO levels and endothelial dysfunction in the aorta of male HAS-2 transgenic mice." (PMID 37176139, 2023). "We can only speculate that the increased EC–EC distances may be associated with lower EC Ca2+ levels, and that they contribute to decreased NO formation and endothelial dysfunction in the aortas of male HAS-2 transgenic mice." (PMID 37176139, 2023).
Hyperglycemia (2 papers, 2022 to 2023). An increased concentration of glucose in the blood. "Hyaluronan (HA), a key element of the ECM, was incrementally secreted under hyperglycemia, and inhibition of PKC-β reduced the expression of HAS2 (hyaluronan synthase 2) mRNA and secretion of HA." (PMID 36060954, 2022).
infertile (2 papers, 2019 to 2024). "This review included a total of 210 infertility women who underwent IVF, with studies using at least three genes of interest - HAS2, GREM1 and PTGS2 - to correlate with oocyte development competency (ODC) outcomes." (PMID 38524634, 2024).
intrahepatic cholangiocarcinoma (2 papers, 2023 to 2025). A carcinoma that arises from the intrahepatic bile duct epithelium in any site of the intrahepatic biliary tree. "During the development of intrahepatic cholangiocarcinoma, activated HSCs transition into myofibroblasts (myCAFs) and inflammatory CAFs (iCAFs), which promote the progression of intrahepatic cholangiocarcinoma through the Has2/HA pathway and HGF/MET pathway, respectively." (PMID 41214328, 2025).
ischemia (2 papers, 2024 to 2025). A hypoperfusion of the BLOOD through an organ or tissue caused by a PATHOLOGIC CONSTRICTION or obstruction of its BLOOD VESSELS, or an absence of BLOOD CIRCULATION. "Increased expression of HAS2 and HA has been reported in ischemia-induced renal fibrosis." (PMID 40075271, 2025).
mesothelioma (2 papers, 2001 to 2021). A usually malignant and aggressive neoplasm of the mesothelium which is often associated with exposure to asbestos. "To investigate the importance of hyaluronan for the malignant properties of mesotheliomas, we have expressed murine hyaluronan synthase 2 (HAS2) in the non-hyaluronan producing mesothelioma cell line, Mero-25." (PMID 11506502, 2001).
myocardial ischemia (2 papers, 2024 to 2025). A disorder of cardiac function caused by insufficient blood flow to the muscle tissue of the heart. "When assessed at 3 weeks post‐myocardial ischemia/reperfusion (MI/R), scars were significantly larger in the Has2 deficient mice." (PMID 41250926, 2025). "Despite prior insights into whole‐body deletion of Has2 in the context of myocardial ischemia/reperfusion injury, the role of fibroblast‐derived hyaluronan after MI has not, however, been defined." (PMID 41250926, 2025).
myopia (2 papers, 2016 to 2017). "However, the exact signal(s) and cause(s) of changes in TGF-β2 and HAS2 expression in the retina and choroid, as well as the manner in which these factors reach the sclera in the development of myopia, remain to be explored in the future." (PMID 29163988, 2017). "Genes mediated by BMP signaling were also implicated, including HAS2 and PTX3 which were up-regulated during hyperopia induction and CTGF which was down-regulated during myopia induction." (PMID 27625591, 2016). "Thus, the data from our study suggest that TGF-β2 and HAS2 may be involved in retinal and choroidal regulation during myopia development." (PMID 29163988, 2017). "TGF-β2 and HAS2 may participate in the formation of myopia in the guinea pig." (PMID 29163988, 2017). "MT3 can inhibit form deprivation myopia, and MT3 treatment can result in changes of retinal and choroidal TGF-β2 and HAS2 mRNA and protein expressions." (PMID 29163988, 2017). "Since TGF-β2 and HAS2 may be involved in the development of form deprivation myopia, in a second step, we studied the effect of MT3 at different tissue concentrations on changes in mRNA and protein expression for TGF-β2 and HAS2." (PMID 29163988, 2017).
neuroblastoma (2 papers, 2014 to 2020). Neuroblastoma (NB) is the most common solid, extracranial childhood tumor. "Cell types that have especially long and numerous plasma membrane protrusions, such as neuroblastoma cells, smooth muscle cells, human fibroblasts, and fibroblasts of Shar Pei dogs with high HAS2 expression have typically high hyaluronan secretion capacity." (PMID 32679746, 2020).
Obesity (2 papers, 2022 to 2025). Accumulation of substantial excess body fat. "Further, we investigated in more detail selected DMRs in TSC22D1, HAS2, GCC1, NCKIPSD from SAT, all being hypermethylated in individuals with obesity and BCCIP, IL1R1 (hypermethylated in lean) and FMNL2 (hypermethylated in individuals with obesity) from OVAT." (PMID 41225618, 2025). "Regarding HA metabolic turnover, the statistically significant up-regulation of HAS1 in individuals with obesity with no relevant gene expression changes in HAS2 and HAS3 or HA degrading enzymes was confirmed in our previous microarray public data." (PMID 35896710, 2022).
renal fibrosis (2 papers, 2022 to 2025). A final common manifestation of a wide variety of chronic kidney diseases characterized by glomerulosclerosis and tubulointerstitial fibrosis. "Our study suggested that an HA/CD44/TGFβ axis triggered by HAS2 overproduction due to COL4A5 deficiency could be strongly implicated in XLAS renal fibrosis." (PMID 40075271, 2025). "The novel contribution of our study is finding that COL4A5 deficiency may lead to HAS2 overexpression and HA accumulation to activate CD44-TGFβ signaling, thereby promoting fibrosis, possibly suggesting that HAS2 and CD44 are potential therapeutic targets for impeding renal fibrosis in XLAS." (PMID 40075271, 2025).
sarcoma (2 papers, 2020 to 2021). A usually aggressive malignant neoplasm of the soft tissue or bone. "Increased expression of UBE2C, CENPE and CREB3L2 compared to normal muscle was detected in 9 of 9 human sarcoma cell lines analyzed, whereas HAS2 expression was detected in only 5 of 9 human sarcoma lines." (PMID 32898143, 2020). "Given that downregulation of Ube2c, Cenpe, Has2 and Creb3l2 by shRNA knockdown diminished mouse sarcoma cell proliferation in vitro, we hypothesized that small molecule inhibitors previously reported to impede the cellular functions of these targets could prove useful in inhibiting their growth." (PMID 32898143, 2020). "As prior work already has validated asparagine starvation as an actionable metabolic vulnerability in sarcomas, this study concentrates on the potential roles of UBE2C, CENPE, HAS2 and CREB3L2 in STS with a focus on RMS." (PMID 32898143, 2020).
squamous cell carcinoma (2 papers, 2017 to 2021). A carcinoma arising from squamous epithelial cells. "USP17 and HAS2 expressions were more prominent in acinar adenocarcinoma (ADC) tumors (82% and 89%, respectively), and in dysplasia (68% and 75%, respectively), compared to squamous cell carcinoma (SqCC; 15% and 17%, respectively)." (PMID 28604766, 2017).
ventricular septal defect (2 papers, 2014 to 2024). The presence of a defect (opening) in the septum that separates the two ventricles of the heart. "A recent study has shown that Hyaluronan Synthase 2 (HAS2) mutations may be involved in the pathogenesis of nonsyndromic ventricular septal defect (VSD) and play a key role in cardiac development." (PMID 39568660, 2024).
autism spectrum disorder (1 paper, 2021). A spectrum of developmental disorders that includes autism, and Asperger syndrome. "Thus, within the critical window of synapse formation in early brain development, the synaptic expression of HAS2 uniquely positions it to prevent the emergence of hyperexcitability commonly observed in neurodevelopmental disorders, such as epilepsy and autism spectrum disorders." (PMID 34685554, 2021).
Burkitt lymphoma (1 paper, 2024). A rare form of malignant mature B-cell non-Hodgkin lymphoma. "Specifically, HAS2 is expressed in the heart, liver, Burkitt’s lymphoma cells (Raji cells), and skeletal muscle." (PMID 39118664, 2024).
cardiac hypertrophy (1 paper, 2025). "To evaluate the impact of fibroblast‐specific Has2 deletion on cardiac hypertrophy and vascular density, we performed wheat germ agglutinin (WGA) staining and isolectin B4 staining 7 days post‐MI." (PMID 41250926, 2025). "Neither cardiac hypertrophy nor vascular density showed significant changes overall due to Has2 deletion." (PMID 41250926, 2025).
childhood asthma (1 paper, 2021). "Although a significant attenuation of Spink5 was thought to be involved in childhood asthma through the interaction with TSLP in Has2+/−-OVA mice, the expression levels of Tslp were not significantly different between WT-OVA and Has2+/−-OVA mice." (PMID 35069543, 2021).
cystitis (1 paper, 2025). Inflammation of the urinary bladder. "Rapid HAS2 and HAS3 upregulation is in correspondence with other studies looking into ketamine induced cystitis." (PMID 40009603, 2025).
disc degeneration (1 paper, 2020). "Similarly, levels of many matrix and matrix-related molecules e.g. Col2, Col9, HAS2, ccn2 are dysregulated during disc degeneration and genetic animal models have helped establish causative link between their expression and disc health." (PMID 33543030, 2020).
Down syndrome (1 paper, 2021). "Interestingly, overexpression of HAS2 has been reported in Down syndrome, which is one of the underling diseases of quasi-MMD12." (PMID 33452387, 2021).
dysplasia (1 paper, 2015). A usually neoplastic transformation of the cell, associated with altered architectural tissue patterns. "In dysplasia and atypical adenomatous hyperplasia,the proportion of HAS-2-positive epithelial cells is lower than in benign lesions, andat this state the hyaluronan content is also increased in cells of benign lesions." (PMID 26352698, 2015).
dysplastic nevi (1 paper, 2013). "First, in dysplastic nevi the expression of HAS1 and HAS2 in the melanocytic cells is increased, although at this stage the amount of hyaluronan is not yet different from benign lesions." (PMID 23560496, 2013).
endometrial tumors (1 paper, 2010). "The epithelial intensities of HAS1, HAS2 and HAS3 immunostainings were significantly stronger in endometrial tumors compared to normal endometrium (p = 0.001, p = 0.004 and p = 0.003, respectively)." (PMID 20875124, 2010).
endometrioid adenocarcinoma (1 paper, 2011). An adenocarcinoma characterized by the presence of malignant glandular epithelial cells resembling endometrial cells. "In endometrioid adenocarcinoma of uterine corpus, the HAS1, HAS2, and HAS3 were expressed in tumor cells as our previous report." (PMID 21904555, 2011).
Endotoxemia (1 paper, 2022). "Endotoxemia led to a significant decrease in the level of mRNA expression of HAS2, COX2 and GREM1 genes in cumulus cells." (PMID 34826885, 2022).
eosinophilia (1 paper, 2021). "Future experiments are needed, for example, to determine whether the Has2 genetic deletion directly affects inflammatory cells and whether the supply of HAS2 enzyme, HMW-HA, and Hsp into the airway abrogates the lung eosinophilia." (PMID 35069543, 2021).
epilepsy (1 paper, 2021). A brain disorder characterized by episodes of abnormally increased neuronal discharge resulting in transient episodes of sensory or motor neurological dysfunction, or psychic dysfunction. "Thus, our data highlights a critical role for synaptic HAS2-HA-CD44 in protecting developing neural networks from the emergence of hyperexcitability and epilepsy through a RhoGTPase signaling axis, by suppressing aberrant Rac1 hyperactivation." (PMID 34685554, 2021).
fibrosarcoma (1 paper, 2022). A malignant mesenchymal fibroblastic neoplasm affecting the soft tissue and bone. "Our data suggests that the nanoscale clustering of hyaluronan at the leading edge of fibroblasts can promote cell motility, and that increased levels of hyaluronan, Hyaluronan Synthase 2, Hyaluronidase 3 and 5 can contribute to the spread and invasion of Infantile fibrosarcoma." (PMID 36400790, 2022).
gastric cancer (1 paper, 2022). A primary or metastatic malignant neoplasm involving the stomach. "Examination of gastric cancer samples from the VARIANZ cohort revealed that HAS2 and SHB are predictive risk factors for response to trastuzumab therapy." (PMID 35264144, 2022). "The gene expression analysis in gastric cancer specimens revealed that HAS2 and SHB were predictive risk factors for trastuzumab therapy response." (PMID 35264144, 2022). "We observed a slight downregulation of HAS2 after trastuzumab, and a strong downregulation after afatinib and cetuximab treatment in gastric cancer cells." (PMID 35264144, 2022). "Since we hypothesized that a regulation in cultured cells induced by anti-HER therapy indicates the importance of the regulated gene as biomarker, we analyzed HAS2 gene expression in gastric cancer patients treated with trastuzumab." (PMID 35264144, 2022). "Analogue to HAS2, SHB gene expression was analyzed in gastric cancer specimens." (PMID 35264144, 2022).
heart failure (1 paper, 2025). Inability of the heart to pump blood at an adequate rate to meet tissue metabolic requirements. "Deletion of Has2 exacerbated heart failure in male mice, as evidenced by reduced cardiac output." (PMID 41250926, 2025).
histiocytic lymphoma (1 paper, 2017). "Since this line of histiocytic lymphoma does not express HAS2, the hyaluronan receptor CD44 was investigated, as this receptor is commonly expressed." (PMID 29023465, 2017). "However, in histiocytic lymphoma that constitutionally does not express HAS2, when CD44 mRNA was tested upon treatment with Apixaban to explore the hyaluronan receptor expression, CD44 was reduced by drug treatment." (PMID 29023465, 2017).
hyperuricemia (1 paper, 2014). An abnormally high level of uric acid. "Hyperuricemia modified the expression pattern of extracellular matrix proteins, upregulating COL1 (P = 0.036) and COMP (P = 0.012) and downregulating HAS2 (P = 0.012)." (PMID 25276832, 2014).
injury (1 paper, 2022). Damage inflicted on the body as the direct or indirect result of an external force, with or without disruption of structural continuity. "Collectively, our results suggest that HAS2 is negatively regulated by miR-200c and contributes to the development of acute liver injury and chronic liver inflammation via hyaluronan-mediated immune signaling." (PMID 35662287, 2022).
Insulin resistance (1 paper, 2025). Increased resistance towards insulin, that is, diminished effectiveness of insulin in reducing blood glucose levels. "Insulin resistance similarly enhances flux through the hexosamine biosynthetic pathway, expanding the intracellular uridine diphosphate N-acetylglucosamine (UDP-GlcNAc) pool, and promoting HAS2 activity/stability via O-linked-GlcNAc-dependent regulation." (PMID 41305610, 2025).
ischemic stroke (1 paper, 2025). A stroke disorder caused by obstruction of blood flow to the brain, due to thrombotic (local blood clot formation) or embolic (due to a blood clot or other material traveling from another site) event. "Elevated expression of hyaluronidase‐1 and HAS2 in astrocytes following ischemic stroke aggravates infarct volume, and suppressing hyaluronidase activity early after stroke can contribute to functional recovery." (PMID 41355840, 2025).
joint disease (1 paper, 2025). "Our findings demonstrate that the impairment in Has2 function could increase OA risk while identifying Has2 as a potential early-stage joint disease biomarker." (PMID 40564043, 2025).
Kabuki syndrome (1 paper, 2022). Kabuki syndrome (KS) is a multiple congenital anomaly syndrome characterized by typical facial features, skeletal anomalies, mild to moderate intellectual disability and postnatal growth deficiency. "For example, Has2 and Cbfb have been implicated in hard palate development, malformations of which are often seen in Kabuki syndrome." (PMID 35871105, 2022).
Kabuki type 2 syndrome (1 paper, 2022). "Interestingly, the GO terms bone development (e.g. Has2) and hard palate development (e.g. Cbfb) are also highlighted, consistent with high-arched palate and other distinctive bone and facial features observed in Kabuki type 2 syndrome caused by KDM6A mutations in human." (PMID 35871105, 2022).
kidney damage (1 paper, 2025). "Similarly, our study revealed that HAS2 is upregulated in XLAS renal tissues, suggesting that increased HAS2 expression is likely harmful in kidney tissue and therefore might be considered a potential biomarker of kidney damage." (PMID 40075271, 2025).
Langer-Giedion syndrome (1 paper, 2023). "Our analysis showed that HAS2 is located outside the predicted critical region for langer-giedion syndrome, making it an unlikely candidate gene for this genetic syndrome." (PMID 37636435, 2023).
laryngeal carcinoma (1 paper, 2021). Carcinoma that arises from the laryngeal epithelium. "Therefore, a model showing the inhibitory effect of circ_0002951/miR-548k/HAS2 pathway in laryngeal cancer was established." (PMID 34093817, 2021). "We suggested that hsa_circ_0002951 as a miR-548k sponge may regulate HAS2 expression and affect the survival rate of patients with laryngeal cancer." (PMID 34093817, 2021). "The screened ceRNA network and circ_0002951/miR-548k/HAS2 pathway based on pRS differences may reveal the potential molecular mechanism of laryngeal cancer lethality." (PMID 34093817, 2021).
left ventricular hypertrophy (1 paper, 2022). Enlargement of the LEFT VENTRICLE of the heart. "Therefore, although Has2 mice do have modestly increased aortic stiffness, it is unlikely to be of sufficient hemodynamic significance to induce left ventricular hypertrophy and dysfunction." (PMID 35671866, 2022).
leiomyosarcoma (1 paper, 2020). An uncommon, aggressive malignant smooth muscle neoplasm, usually occurring in post-menopausal women. "In human leiomyosarcomas (LMS), expression of UBE2C was found in 12 of 26 (46%), of CENPE in 7 of 26 (27%), of HAS2 in 7 of 26 (25%) and of CREB3L2 in 20 of 27 (74%) human leiomyosarcoma cores." (PMID 32898143, 2020).
liver inflammation (1 paper, 2022). "Taken together, our results suggest that Has2 deficiency in HSCs ameliorates acute CCl4-induced liver inflammation." (PMID 35662287, 2022).
lung disease (1 paper, 2019). "Furthermore a recent study suggests that maintenance of HAS2 expression prevents fibroblast senescence leading to enhanced fibrotic lung disease." (PMID 29933044, 2019).
lymph node metastasis (1 paper, 2025). "Slug and Vimentin levels were significantly increased in patients with T-stage ≥ T3, while patients who had lymph node metastasis had significantly higher HAS-2, SNAI1, TWIST1, N-Cadh, Slug, and MMP-9." (PMID 40149256, 2025).